ST3GAL4 (ST3 beta-galactoside alpha-2,3-sialyltransferase 4)
Description:
A beta-galactoside alpha2-3 sialyltransferase involved in terminal sialylation of glycoproteins and glycolipids. Catalyzes the transfer of sialic acid (N-acetyl-neuraminic acid; Neu5Ac) from the nucleotide sugar donor CMP-Neu5Ac onto acceptor Galbeta-(1->3)-GalNAc- and Galbeta-(1->4)-GlcNAc-terminated glycoconjugates through an alpha2-3 linkage. Plays a major role in hemostasis. Responsible for sialylation of plasma VWF/von Willebrand factor, preventing its recognition by asialoglycoprotein receptors (ASGPR) and subsequent clearance. Regulates ASGPR-mediated clearance of platelets (By similarity). Participates in the biosynthesis of the sialyl Lewis X epitopes, both on O- and N-glycans, which are recognized by SELE/E-selectin, SELP/P-selectin and SELL/L-selectin. Essential for selectin-mediated rolling and adhesion of leukocytes during extravasation. Contributes to adhesion and transendothelial migration of neutrophils likely through terminal sialylation of CXCR2 (By similarity). In glycosphingolipid biosynthesis, sialylates GM1 and GA1 gangliosides to form GD1a and GM1b, respectively. Metabolizes brain c-series ganglioside GT1c forming GQ1c (By similarity). Synthesizes ganglioside LM1 (IV3Neu5Ac-nLc4Cer), a major structural component of peripheral nerve myelin.
Synonyms: ST3GalIV; CGS23; NANTA3; SIAT4C; STZ; SAT3; FLJ11867; SIAT4; ST-4; ST3GalA.2; gal-NAc6S
Tractability: Antibody: UniProt places it where antibodies can reach, with medium confidence; UniProt predicts a signal peptide or a membrane-spanning region; its Gene Ontology location is reachable by antibodies, with medium confidence. PROTAC: ubiquitination databases record sites on it.
Gene: Protein-coding gene on chromosome 11 (126,354,677 to 126,440,344, forward strand). Ensembl gene ENSG00000110080.
Subcellular location: Golgi apparatus, Golgi stack membrane; Secreted
Pathways (Reactome):
Metabolism of proteins: N-Glycan antennae elongation; Sialic acid metabolism; Termination of O-glycan biosynthesis
Disease: Maturation of protein 3a; Maturation of spike protein
Metabolism: Keratan sulfate biosynthesis; Lewis blood group biosynthesis
Signal Transduction: Pre-NOTCH Processing in Golgi
Gene Ontology:
Molecular function: beta-D-galactosyl-(1->3)-N-acetyl-beta-D-galactosaminide alpha-2,3- sialyltransferase; beta-galactoside (CMP) alpha-2,3-sialyltransferase activity; N-acetyllactosaminide alpha-2,3-sialyltransferase activity; sialyltransferase activity
Biological process: cognition; glycolipid biosynthetic process; glycoprotein biosynthetic process; oligosaccharide biosynthetic process; positive regulation of leukocyte tethering or rolling; protein N-linked glycosylation; sialylation; keratan sulfate proteoglycan biosynthetic process; positive regulation of blood coagulation; protein O-linked glycosylation via N-acetyl-galactosamine; viral protein processing
Cellular component: membrane; Golgi membrane; extracellular region; Golgi cisterna membrane
Genetic constraint (gnomAD): Loss-of-function variants: 24 observed, 44.31 expected, observed/expected ratio (o/e) 0.54, 90% interval 0.39 to 0.76. The upper end of that interval is the gene's LOEUF score, 0.76, which puts it in group 3 of 6, group 1 being the genes least tolerant of losing a copy. Missense variants: 311 observed, 450.86 expected, observed/expected ratio (o/e) 0.69, 90% interval 0.63 to 0.76. Synonymous variants: 135 observed, 171.16 expected, observed/expected ratio (o/e) 0.79, 90% interval 0.69 to 0.91.
Homologues: Orthologues: chimpanzee ST3GAL4 (99% identical), macaque ST3GAL4 (98% identical), dog ST3GAL4 (94% identical), rabbit ST3GAL4 (92% identical), rat Dcps (92% identical), mouse St3gal4 (91% identical), pig ST3GAL4 (91% identical), guinea pig ST3GAL4 (83% identical), tropical clawed frog st3gal4 (57% identical), zebrafish st3gal4 (50% identical). Paralogues in human: ST3GAL3 (36% identical), ST3GAL6 (36% identical), ST3GAL5 (32% identical), ST6GALNAC1 (26% identical), ST3GAL2 (23% identical), ST6GALNAC2 (23% identical), ST3GAL1 (23% identical), ST6GAL2 (22% identical), ST6GAL1 (22% identical), ST6GALNAC5 (18% identical), ST6GALNAC4 (17% identical), ST6GALNAC6 (17% identical), and 2 more.
Diseases named in the same sentence as ST3GAL4 in open-access papers:
ST3GAL4 is named in the same sentence as 75 diseases in open-access papers, as found by Europe PMC text mining. Sharing a sentence is not in itself a finding about the gene and the disease. The quoted sentences say what the papers report.
gastric cancer (13 papers, 2013 to 2023). A primary or metastatic malignant neoplasm involving the stomach. "We evaluate the response to targeted treatment of glycoengineered gastric cancer cell models overexpressing the sialyltransferases ST3GAL4 or ST3GAL6 by subjecting 3D spheroids to the tyrosine kinase inhibitor crizotinib." (PMID 31979110, 2020). "We show here that 3D spheroids of ST3GAL4 or ST3GAL6 overexpressing MKN45 gastric cancer cells are less affected by the inhibitor." (PMID 31979110, 2020). "ST3GAL4 KD have also been reported to decrease the ability of cancer cells to adhere to selectins and to invade and migrate in vitro in gastric cancer." (PMID 32872308, 2020). "Similar results on higher ST3GAL4 relative to ST3GAL3 expression have also been reported in gastric carcinoma." (PMID 32872308, 2020). "Gastric carcinoma MKN45 cells stably transfected with the full-length ST3GAL4 gene were characterised by glycomic and sialoproteomic analysis." (PMID 27077082, 2016). "Our results showed that the expression of ST3GAL4 in MKN45 gastric cancer cells leads to the synthesis of SLex antigens and to an increased invasive phenotype both in vitro and in the in vivo CAM model." (PMID 23799130, 2013). "In conclusion, the expression of ST3GAL4 leads to SLex antigen expression in gastric cancer cells which in turn induces an increased invasive phenotype through the activation of c-Met, in association with Src, FAK and Cdc42, Rac1 and RhoA GTPases activation." (PMID 23799130, 2013). "Likewise, increased α-2,3 sialylation by ST3GAL4 led to increased metastatic potential of gastric cancer cells and correlates with poor prognosis." (PMID 33921986, 2021). "In addition, our group has recently shown that overexpressing a sialyltransferase, ST3GAL4, in gastric cancer cells leads to SLe(x) antigen expression which in turn induces a more invasive phenotype." (PMID 25850034, 2015). "In this study we determined the capacity of ST3GAL3 and ST3GAL4 sialyltransferases to synthesize the SLex antigen in MKN45 gastric carcinoma cells and evaluated the effect of SLex overexpression in cancer cell behavior both in vitro and in vivo using the chicken chorioallantoic membrane (CAM) model." (PMID 23799130, 2013). "In a previous work, the human gastric cancer cell line MKN45, which showed low or undetectable expression levels of the sialyltransferases ST3GAL4 and ST3GAL6, respectively, was stably transfected with the expression vector containing the respective full length cDNA encoding for ST3GAL4 and ST3GAL6." (PMID 31979110, 2020). "The potential mechanism, underlying the increased invasive phenotype in overexpressed ST3GAL4 in gastric cancer cells, which is accompanied by a concomitant increase in sLex, could involve the activation of tyrosine kinase receptors such as c-Met and its associated downstream signaling effectors." (PMID 32872308, 2020).
melanoma (8 papers, 2021 to 2026). A malignant, usually aggressive tumor composed of atypical, neoplastic melanocytes. "Similar to our findings tissue, melanoma cell lines are enriched in the expression of genes associated with the metabolism of sialic acid, including the sialyltransferases ST3GAL4 and ST3GAL6." (PMID 38384845, 2024). "Consistently, the number of migrated cells was remarkably reduced in ST3GAL4-deficient melanoma cells." (PMID 34544412, 2021). "A lowered migration ratio was observed in ST3GaL4-deficient melanoma cells." (PMID 36982460, 2023). "As miR-1180-3p might regulate the biological behavior of melanoma cells by targeting ST3GAL4, we treated ST3GAL4-deficient melanoma cells with miR-1180-3p mimics and inhibitors." (PMID 34544412, 2021). "This study provides structural evidence for targeted therapeutic strategies in ST3GAL4-overexpressing melanoma and establishes foundations for age-stratified immunotherapy." (PMID 42304383, 2026). "The manipulation of miR-1180-3p expression allowed for the identification of the ST3GAL4 boosting effect on melanoma cell migration." (PMID 36982460, 2023). "MAN2B1 and ST3GAL4 exhibited higher expression in melanoma patients, and MAN2C1 was downregulated in tumor tissues." (PMID 34544412, 2021). "Functional analysis and target gene prediction found that ST3GAL4 was a potential target and highly expressed in melanoma tissues and was negatively regulated by miR-1180-3p." (PMID 34544412, 2021). "Moderating the activity of miR-1180-3p and ST3GAL4 can be used as a therapeutic method in melanoma." (PMID 36982460, 2023). "Mechanistically, miR-1180-3p expression negatively regulates malignant cell traits, such as proliferation, invasion and migration, in an in vitro melanoma cell model, possibly through post-transcriptional inhibition of the melanoma related-gene ST3GAL4 expression." (PMID 38201222, 2023). "Besides, the level of exosomal miR-1180-3p was negatively correlated with the proliferation, migration and invasion of melanoma cells, and reduced the high expression of ST3GAL4 in melanoma cells." (PMID 36203417, 2022). "Knockdown of ST3GAL4 hindered the malignant phenotype of melanoma cells." (PMID 34544412, 2021). "In addition, decreased miR-1180-3p expression promoted the development of melanoma by targeting ST3GAL4." (PMID 34544412, 2021). "In addition, decreased miR-1180-3p expression promoted the proliferation of melanoma cells by elevating ST3GAL4." (PMID 34544412, 2021). "To date, few studies have investigated the role of ST3GAL4 in the development of melanoma." (PMID 34544412, 2021). "In addition, the invasion ability was attenuated when the expression of ST3GAL4 was inhibited in melanoma cells." (PMID 34544412, 2021). "Interestingly, ST3GAL4 was specifically highly expressed in melanoma." (PMID 34544412, 2021). "Importantly, the miR-1130-3p/ST3GAL4 axis could be a therapeutic target for melanoma treatment." (PMID 34544412, 2021).
ovarian carcinoma (6 papers, 2017 to 2024). A malignant neoplasm originating from the surface ovarian epithelium. "Increased ST3GAL4 mRNA levels were associated with worse progression free survival in patients with a diagnosis of ovarian cancer when separated by the median (logrank p = 0.022, hazard ratio = 0.86) (kmplot.com)." (PMID 33579350, 2021). "The additional profiling of other sialyltransferase genes, ST6GAL2, ST3GAL4 and ST3GAL5, was found to display varying gene expression levels between both cancer tissue types and across all tested ovarian cancer cell lines." (PMID 28853212, 2017).
renal cell carcinoma (6 papers, 2015 to 2021). "Increased level of ST3GAL4 mRNA in renal cell carcinoma (RCC) has been shown to be associated with favorable prognosis." (PMID 31117943, 2019). "Conversely, the down-regulation of ST3GAL4 has been observed in colorectal cancer tissues and human renal cell carcinoma." (PMID 25923697, 2015).
pancreatic cancer (5 papers, 2020 to 2024). "Previous studies have shown that ST3GAL4 affects several biological behaviors in tumors such as proliferation, invasion, and migration in non-small cell lung cancer and pancreatic cancer cells." (PMID 38212768, 2024). "It has been demonstrated that ST3GAL3 and ST3GAL4 increase the adhesion, motility, and migration of pancreatic cancer cells in vitro and the potential for metastasis in vivo." (PMID 36547200, 2022). "The migration, invasion, and E-selectin-dependent adhesion of pancreatic cancer cells were consistently reduced when ST3GAL3 or ST3GAL4 expression was downregulated." (PMID 36547200, 2022). "The overexpressed ST3GAL3 and ST3GAL4 in pancreatic cancer increase the biosynthesis of the sialic acid-Lewis (sLe) antigen, thus promoting tumor metastasis." (PMID 36092699, 2022). "ST3GAL3 and ST3GAL4 have been shown to promote pancreatic cancer cell adhesion, motility and migration in vitro and to enhance metastatic potential in vivo." (PMID 33921986, 2021). "Consistently, downregulation of either ST3GAL3 or ST3GAL4 decreased pancreatic cancer cell migration, invasion and E-selectin-dependent adhesion." (PMID 33921986, 2021). "In this work, we have addressed the impact of the downregulation of the α2,3-sialyltransferases ST3GAL3 and ST3GAL4 (which regulate sLex and sLea biosynthesis) on migration, invasion and E-selectin-dependent adhesion of pancreatic cancer cells." (PMID 32872308, 2020). "ST3GAL3 and ST3GAL4 were knocked down via shRNA in two pancreatic cancer cell lines, BxPC-3 and Capan-1, whose scramble (SC) control cells display high to moderate levels of sLex." (PMID 32872308, 2020). "Overall, we have shown that STs, and in particular ST3GAL4 and ST3GAL3 that lead to the sLex/a biosynthesis can be considered as potential therapeutic targets against pancreatic cancer." (PMID 32872308, 2020). "To further investigate the functional importance of ST3GAL4 and ST3GAL3 in the binding of pancreatic tumor cells to E-selectin, we also analyzed this adhesive interaction under dynamic flow conditions using a microfluidic system." (PMID 32872308, 2020).
Anxiety (4 papers, 2015 to 2025). Intense feelings of nervousness, tension, or panic often arise in response to interpersonal stresses. "Urinary biomarkers of temporal lobe epilepsy (TLE) were identified in amygdala-kindling mice and for depression and anxiety in sialyltransferase St3gal4-deficient mice." (PMID 37861875, 2022). "We previously reported that ST3 beta-galactoside alpha-2,3-sialyltransferase IV (St3gal4)-deficient mice showed symptoms of anxiety and depression." (PMID 32084196, 2020). "We have developed a mouse model of depression/anxiety in mice deficient in the St3gal4 gene." (PMID 32084196, 2020).
cervical cancer (4 papers, 2018 to 2022). A primary or metastatic malignant neoplasm involving the cervix. "Other studies also have shown that the expression level of ST3GAL4 in cervical cancer cells was also reduced." (PMID 34200006, 2021). "Moreover, it was found that high expression of ST6GAL1 was associated with more invasive properties of cervical cancer and that the reduced expression of ST3GAL1, ST3GAL3, and ST3GAL4 may also contribute to the characteristics of cervical cancer." (PMID 30375371, 2018).
colon carcinoma (4 papers, 2020 to 2023). "In colon carcinoma cells, ST3GAL4 targeting by miR-370 inhibits P-selectin-induced cell adhesion by targeting ST3GAL4." (PMID 36555445, 2022). "Intriguingly, the induction of epithelial-mesenchymal transition (EMT) in colon cancer led to the upregulation of FUT3, ST3GAL3 and ST3GAL4, which are implicated in the final steps of the biosynthesis of sLex/a, suggesting a significant link between those Lewis antigens and EMT in colon carcinoma." (PMID 32872308, 2020). "Previous study indicates that NEU4 desialylates cell surface sLeA/X to LeA/X without affecting the expression of ST3GAL3, ST3GAL4, FUT3, and FUT7 in colon cancer cells." (PMID 34135905, 2021).
viral infection (4 papers, 2017 to 2025). "Although sialic acid presentation is important in EV-D68 infections, a previous gene trap showed that ST6GAL1, which mainly catalyzes 2,6-linked sialic acid formation, is considerably more important than ST3GAL4 in HAP-1 cells for viral infection." (PMID 28446605, 2017). "We first determined the dependency of virus infection efficiency on the density and specificity of Sia receptors on the surface of HEKΔSia cells that were co-transfected with a concentration range of sialyltransferases ST6Gal1 or ST3Gal4." (PMID 35831293, 2022). "We hypothesized that ST3GAL4-disrupted cells had a selective advantage over other gene-disrupted cells in the presence of the enterovirus and that other genes essential for the viral infection could be identified using a dropout library in which the three sgRNAs specific to ST3GAL4 were excluded." (PMID 28446605, 2017). "Results from the screen and subsequent analysis highlighted that several genes involved in sialic acid synthesis, including ST3GAL4, ST6GAL1, and SLC35A1, are important for viral infection." (PMID 40767522, 2025). "However, we could only identify ST3GAL4, not ST6GAL1, as an essential factor for viral infection in HeLa cells." (PMID 28446605, 2017).
colitis (3 papers, 2023 to 2025). Inflammation of the colon. "Surprisingly, the St3gal4-deficient mice or wild-type mice fed with 3′-SL-deficient milk from St3gal4 knock-out mice were more resistant to DSS-induced colitis than the wild-type mice and St3gal4 knock-out mice fed with normal milk." (PMID 38140362, 2023). "Our findings can be extended to a previous study of the inhibition of SA release by the knockout of the α2,3 sialyltransferase St3gal4, which reduced Enterobacteriaceae abundance and alleviated colitis in DSS-treated mice." (PMID 37069691, 2023).
coronary artery disease (3 papers, 2016 to 2022). "Genome-wide association studies have demonstrated associations between ST3GAL4 gene variants or single-nucleotide polymorphisms and lipid traits, including high ApoB levels, total cholesterol, triglyceride levels, and coronary artery disease." (PMID 32084196, 2020). "St3gal4 is a sialyltransferase and in humans SNPs or gene variants of ST3GAL4 affect lipid traits as well as the subsequent development of coronary artery disease." (PMID 32084196, 2020).
COVID-19 (3 papers, 2021 to 2024). A disease caused by infection with severe acute respiratory syndrome coronavirus 2. "However, we detected increased ST3GAL4 mRNA expression in the severe COVID-19 cohort, which positively correlated with the summation of all sialic acid content on IgM." (PMID 38195739, 2024). "We observed the presence of α-2,3 sialylation on IgM, suggesting some of the increased sialylation on IgM isolated from severe COVID-19 patients could be attributed to ST3GAL4 activity." (PMID 38195739, 2024). "Taken together, the increase in ST3GAL4 during COVID-19 may be exerting proinflammatory downstream effects during disease pathogenesis." (PMID 37398192, 2023). "The differences in glycosylation observed between IgG and IgM from the same COVID-19 patients suggest that ST3GAL4 could add sialic acid to IgM." (PMID 37398192, 2023). "In addition, the transcriptomic level of ST6GAL1 and ST3GAL4 also increased in the BMMCs from COVID-19 patients." (PMID 34349096, 2021). "Therefore, the increase in ST3GAL4 during severe COVID-19 may be exerting proinflammatory effects during severe COVID-19 pathogenesis through IgM and other glycoproteins." (PMID 38195739, 2024). "The expression of the α−2,3 sialyltransferase ST3GAL4 and the O-glycan α−2,6 sialyltransferase ST6GALNAC2 were significantly elevated in the severe COVID-19 cohort." (PMID 37398192, 2023). "Moreover, glycosylation of IgM correlates with circulating immune cell glycosyltransferase expression of ST3GAL4 and MAN1A2, previously reported clinical markers of COVID-19 severity, and elevations in cytokines IL-16 and IL-18." (PMID 37398192, 2023). "Interestingly, the ST6GAL1 did not significantly differ between COVID-19 severity suggesting that a portion of the increased sialylation on IgM is due to the α−2,3 sialyltransferase ST3GAL4." (PMID 37398192, 2023).